ATM (ATM serine/threonine kinase)
Diseases named in the same sentence as ATM in open-access papers (continued):
Sharing a sentence is not in itself a finding about the gene and the disease.
breast cancer (continued). "One possible explanation is that the impact of PGS313 on OS may be confounded by other genetic risk factors, many of which have yet to be identified; several recent papers have found that PGS313 stratifies breast cancer risk in CHEK2, PALB2, and ATM carriers but not BRCA1/2 carriers." (PMID 38704641, 2024). "When breast cancer cells are treated with radiotherapy, chemotherapy or PARP inhibitors, the resulting DNA damage could be still repaired through the activation of specific DNA repair genes, such as ATM, BRCA1/2, RAD51, DNA-PK etc., thus cells survive and continue to proliferate." (PMID 30234015, 2018). "The level of adverse side effects in the Norwegian breast cancer patients or risk of IBTR in the American breast cancer cases were then compared between the group of patients with and the group of patients without any detected variation in the ATM gene fulfilling these criteria." (PMID 17623063, 2007). "HRD extends beyond BRCA1/BRCA2 mutations to include non-BRCA genes (RAD51C/RAD51D, BRIP1, BARD1, ATM, PALB2), broadening actionable targets across ovarian and breast cancer subtypes, including HER2-positive (30–40%) and luminal subtypes (15–25%)." (PMID 40864792, 2025). "We have also demonstrated that variation in ATM and CHEK2 does not contribute significantly to breast cancer in Orcadians." (PMID 39438716, 2024). "In their study 60% (12/20) of PALB2 and 58% (7/12) of ATM/CHEK2 carriers with breast cancer underwent RRM compared to 57% (4/7) and 29% (2/7) of those without breast cancer, respectively." (PMID 36054727, 2022). "This is consistent with previous reports in breast cancer and cell line experiments where Signature 3 was only detected for BRCA1/2, PALB2 and RAD51C genes but not ATM or CHEK2." (PMID 33917078, 2021). "Deficiency in the DNA damage response factor ataxia-telangiectasia mutated (ATM) can also sensitize tumors to PARP inhibitors, raising the question of whether the presence or absence of 53BP1 can predict sensitivity of ATM-deficient breast cancer to these inhibitors." (PMID 27613518, 2016). "The results indicate that common variation in the ATM, CHEK2 or ERBB2 genes does not have a role in breast cancer aetiology or progression." (PMID 17132159, 2006). "However, patients with breast cancer without ICB therapy and with low ATM expression exhibit lower OS rates than those with high ATM expression." (PMID 37174688, 2023).
ataxia telangiectasia (512 papers, 2000 to 2026). Ataxia-telangiectasia is the association of severe combined immunodeficiency (affecting mainly the humoral immune response) with progressive cerebellar ataxia. "Some autosomal-recessive tumor predisposition syndromes, such as ataxia telangiectasia, caused by biallelic variants in the ATM gene, have also been linked to glioma predisposition." (PMID 41546701, 2026). "Biallelic ATM GVs cause ataxia telangiectasia characterized by a predisposition to tumors, including medulloblastoma and cerebellar astrocytoma, immunodeficiency, and cerebellar degeneration among other features." (PMID 41546701, 2026). "For example, ATM, in recessive forms, is associated with hematologic malignancy in children affected with ataxia telangiectasia." (PMID 41495781, 2026). "Ataxia telangiectasia (AT) is a rare multisystem disorder caused by the loss of functional ATM protein, leading to immunodeficiency, cancer predisposition, neurodegeneration, diabetes, heart failure, and premature aging." (PMID 41771847, 2026). "Pathogenic germline variants in the ATM gene are characteristic of the inherited disorder ataxia telangiectasia (A‐T), which confers a lifelong predisposition to breast, ovarian, prostate, and pancreatic cancers." (PMID 40622001, 2025). "Biallelic germline pathogenic variants in ATM (Ataxia-Telangiectasia Mutated) cause A-T (Ataxia-Telangiectasia), a rare autosomal recessive neurodegenerative disorder associated with immunodeficiency and high cancer risk." (PMID 40451289, 2025). "This ATM variant has been previously reported in patients with classic ataxia–telangiectasia and is considered a recurrent pathogenic variant." (PMID 41300699, 2025). "In Families 9, 11, and 12, associated with Ataxia-Telangiectasia (AT), each proband exhibited biallelic mutations in the ATM gene." (PMID 40635703, 2025). "Louis-Bar syndrome is a hereditary disorder caused by mutations in the ATM gene, which plays a critical role in DNA repair and genomic stability maintenance." (PMID 41451872, 2025). "The two cases presented here, autosomal recessive cutis laxa type 1A caused by a novel FBLN5 variant and ataxia telangiectasia associated with a pathogenic ATM variant, illustrate the diagnostic difficulties related to overlapping clinical features." (PMID 41300699, 2025). "Ataxia Telangiectasia is a genetic neurodegenerative disorder resulting from a deficiency in the action or regulation of the gene Ataxia Telangiectasia Mutated (ATM), which is involved in the DNA damage response (DDR) pathway." (PMID 40083875, 2025). "The diagram illustrates that nonsense mutations and large deletions result in the most severe forms of Louis-Bar syndrome due to the complete loss of functional ATM protein synthesis." (PMID 41451872, 2025). "Ataxia-telangiectasia (A-T) is a rare autosomal recessive disorder caused by mutations in the ATM gene, which codes for the ATM protein kinase." (PMID 40880371, 2025). "The top frequent gene was ATM, which encodes a protein crucial for the DNA damage response and cell cycle regulation, and mutations in this gene cause ataxia-telangiectasia, a disorder characterized by neurological degeneration." (PMID 39788962, 2025). "The most common and best studied disorder of DNA repair and genomic stability is ataxia‐telangiectasia (AT), caused by mutation of the ATM gene and likely the third most common recessive ataxia in most regions." (PMID 40464291, 2025). "The first was diagnosed with autosomal recessive cutis laxa type 1A (ARCL1A) attributable to a homozygous FBLN5 variant, whereas the second was confirmed with ataxia–telangiectasia (A–T) resulting from a heterozygous ATM frameshift mutation." (PMID 41300699, 2025). "Individuals with ataxia–telangiectasia possessed a homozygous ATM variant, validating autosomal recessive inheritance." (PMID 40806973, 2025).
ataxia telangiectasia (continued). "The underlying cause of Louis-Bar syndrome is mutations in the ATM (ataxia-telangiectasia mutated) gene, which is located on chromosome 11." (PMID 41451872, 2025). "In humans, mutations in ATM cause ataxia telangiectasia (AT), an autosomal recessive inherited disease characterized by a strong predisposition to malignancy, cerebellar degeneration, radiosensitivity, immune deficiencies, premature ageing and sterility." (PMID 41248173, 2025). "Classical ligand docking simulations, such as those used in Ataxia Telangiectasia, enable the prediction of drug binding to Ataxia-Telangiectasia Mutated (ATM) protein targets." (PMID 41249457, 2025). "Ataxia-Telangiectasia (A-T) is caused by biallelic Ataxia-Telangiectasia Mutated (ATM) protein mutations and is hallmarked by neurodegeneration, immunodeficiency and cancer susceptibility." (PMID 41065894, 2025). "The second case concerned an adolescent with progressive neurodegeneration, granulomatous skin lesions, and chronic pancreatitis, who was identified with a heterozygous pathogenic ATM:c.4828dup variant, confirming ataxia–telangiectasia." (PMID 41300699, 2025). "Ataxia–telangiectasia is a rare autosomal recessive disorder caused by mutations in the ATM gene, located on chromosome 11q22.3 (MIM 208900)." (PMID 40565533, 2025). "Mutations in the ATM gene cause Ataxia-Telangiectasia and were also shown to cause increased single-strand break loads due to elevated reactive oxygen species (ROS)." (PMID 40966285, 2025). "Ataxia–telangiectasia (A–T) is a rare, autosomal recessive, multisystem disorder caused by mutations in the Ataxia–Telangiectasia Mutated (ATM) gene." (PMID 40959764, 2025). "The discovery of a novel FBLN5 variant expands the mutational landscape of cutis laxa type 1A, while the ATM variant broadens phenotypic recognition of ataxia telangiectasia." (PMID 41300699, 2025). "There are many other important molecules in DNA repair from radiation damage, including ATM, MRE11, NBS1, and RAD50; notably, ATM is the protein mutated in ataxia telangiectasia, a disease characterized by extreme human radiosensitivity." (PMID 40563819, 2025). "There have been no prior reported cases of the ATM gene in CCV patients; however, the ATM gene is also associated with ataxia telangiectasia (Louis-Bar syndrome), a pediatric telangiectatic disorder." (PMID 40995169, 2025). "The second concerns an adolescent with a heterozygous pathogenic ATM variant, manifesting as ataxia-telangiectasia with granulomatous skin lesions, bronchiectasis, and progressive neurological decline." (PMID 41300699, 2025). "Ataxia-telangiectasia (A-T) is a rare autosomal recessive disorder caused by pathogenic ATM gene variants, characterised by progressive cerebellar ataxia, telangiectasia, immunodeficiency, and cancer predisposition." (PMID 41044616, 2025). "Subsequent studies extended these findings to genetic disorders like Ataxia–Telangiectasia, where gentamicin treatment of patient-derived lymphoblastoid cells led to the production of functional Ataxia Telangiectasia Mutated (ATM) protein." (PMID 40801647, 2025). "Ataxia-telangiectasia (A-T) is a rare autosomal recessive disorder caused by mutations in the ATM gene, which encodes a serine/threonine-protein kinase." (PMID 40564629, 2025). "Ataxia–telangiectasia (A–T) is a rare, autosomal recessive, multisystem disorder caused by mutations in the Ataxia–Telangiectasia Mutated (ATM) gene and is characterized by a devastating and progressive neurological pathology." (PMID 40959764, 2025). "The physiological significance of the chromatin-R-loop-ATM axis is also supported by the phenotype of a murine model with ATM-deficiency mimicking the severe human neurological disorder Ataxia Telangiectasia (AT)." (PMID 40859031, 2025). "Ataxia-telangiectasia (A-T), also called Louis-Bar syndrome, is a recessive disorder caused by primary immunodeficiency and mutation of the A-T mutated (ATM) gene." (PMID 40452674, 2025).
ataxia telangiectasia (continued). "Genetic testing in 2024 identified a heterozygous pathogenic ATM frameshift variant (c.4828dup, p.Arg1610Lysfs*3), confirming the diagnosis of ataxia–telangiectasia." (PMID 41300699, 2025). "Ataxia telangiectasia (A-T) is a rare neurodegenerative syndrome caused by variations in the ataxia-telangiectasia mutant (ATM) protein." (PMID 39853455, 2025). "Whole-exome sequencing identified heterozygous variants c.1564-165del, p.(Glu5221lefsTer43), and c.7630-2A>C in the serine/threonine-protein kinase ATM (ataxia-telangiectasia mutated) gene, confirming the diagnosis of ataxia-telangiectasia." (PMID 40564629, 2025). "In this case, flow cytometry showed an absence of T cells (T−B+NK+) and the patient’s NGS study showed a homozygous pathogenic variant in the ATM gene (c.8585-2A>C) associated with ataxia telangiectasia (AT)." (PMID 39982345, 2025). "Pathogenic germline ATM mutations were identified in individuals with Ataxia-Telangiectasia (AT), with an autosomal recessive inheritance model." (PMID 41378284, 2025). "Germ-line mutations in the ataxia telangiectasia mutated (ATM) gene lead to ataxia-telangiectasia syndrome, manifested by increased susceptibility to malignancies." (PMID 38956367, 2024). "ATM pathogenic variants, such as homozygous or compound heterozygous changes, cause ataxia telangiectasia, a syndromic disease characterized by progressive cerebellar ataxia, oculomotor apraxia, immunodeficiency, and enhanced cancer predisposition." (PMID 38397209, 2024). "Germline mutations in ATM can result in the neurological disorder Ataxia-Telangiectasia (A-T), characterized by traits including ataxia, cerebral degeneration and increased cancer risk." (PMID 38933336, 2024). "Cerebellar neurodegenerationis a classical feature of ataxia telangiectasia (A-T), an autosomal recessive condition caused by loss-of-function mutation of the ATM gene, a gene with multiple regulatory functions." (PMID 37120494, 2024). "Aminoglycosides were also evaluated in neurological diseases, such as Ataxia–Telangiectasia (A-T), that encode the ATM gene." (PMID 38543100, 2024). "Ataxia-telangiectasia (A-T) is a neuroimmunological disorder brought on by mutated pathogenic variations of ATM gene." (PMID 39281240, 2024). "Homozygous mutations in ATM lead to ataxia-telangiectasia, a rare autosomal recessive condition characterized by cerebellar degeneration, oculocutaneous telangiectasia, and immunodeficiency." (PMID 39543654, 2024). "ATM, the gene mutated in the disorder ataxia-telangiectasia, is a protein kinase that is a central mediator of responses to DNA double-strand breaks in cells." (PMID 38612913, 2024). "In mice with ataxia telangiectasia, it was postulated that ATM deficiency leads to osteoporosis, mainly as a result of hypogonadism-induced bone resorption together with compromised osteoblast differentiation." (PMID 39917433, 2024). "Ataxia-telangiectasia (A-T) is an ultrarare autosomal recessive disorder caused by mutations in the Ataxia-telangiectasia mutated (ATM) gene, located on the long arm (q) of chromosome 11 (11q22–23)." (PMID 39764161, 2024). "In humans, mutations in ATM result in ataxia-telangiectasia (A-T), a multisystem disease that includes a prominent neurodegenerative phenotype mostly affecting the cerebellum." (PMID 39085642, 2024). "Bi-allelic deleterious variants in the ATM gene cause a rare autosomal recessive neurodegenerative disease, ataxia–telangiectasia, which occurs in approximately 1 per 880,000 live births." (PMID 39684352, 2024). "Ataxia‐telangiectasia (A‐T) is a multisystem disease caused by loss of activity of the protein kinase ataxia telangiectasia mutated (ATM) due to nonsense or missense mutations in the ATM gene." (PMID 38525112, 2024).
ataxia telangiectasia (continued). "Homozygous or compound heterozygous variants in ATM are associated with ataxia‐telangiectasia, a recessive disorder which is characterized by cerebellar ataxia, telangiectases, and a predisposition to malignancy." (PMID 39180521, 2024). "An intronic mutation within the ATM gene leading to the abrogation of a putative U1 snRNA binding site away from the 5′ss of the upstream exon is associated with ataxia-telangiectasia." (PMID 39086841, 2024). "In the ATM gene, mutations resulting in defective splicing constitute about 48% in patients with ataxia-telangiectasia." (PMID 39944559, 2024). "Complete ATM loss of function caused by biallelic ATM pathogenic variants results in the disease ataxia telangiectasia (AT), characterized by immunodeficiency, neurological degeneration and predisposition to cancer." (PMID 38338943, 2024). "For example, loss of ATM in ataxia-telangiectasia patients impairs mitochondrial function and mitophagy independent of its DNA damage response." (PMID 36966227, 2023). "ATM depletion is associated with the multisystemic neurodegenerative syndrome ataxia–telangiectasia (A–T)." (PMID 37296624, 2023). "Bi-allelic pathogenic variants in this gene cause Ataxia Telangiectasia (AT), while carriers of ATM pathogenic variants are at increased risk of cancer depending on the pathogenicity of the variant they carry." (PMID 38327652, 2023). "Ataxia Telangiectasia (A‐T) is a rare genetic syndrome caused by biallelic mutations in the Ataxia Telangiectasia Mutated (ATM) gene that codes for a protein kinase of the same name, belonging to the PI3 kinase‐like kinase." (PMID 37345209, 2023). "Individuals with ataxia telangiectasia due to loss of the tumor suppressor gene ataxia telangiectasia mutated (ATM) present during adolescence." (PMID 37569479, 2023). "Loss of the mitochondrial ROS-sensing function of ATM caused cellular ROS accumulation and oxidative stress in ataxia telangiectasia (AT)." (PMID 37511215, 2023). "Homozygous mutations in the ATM gene are associated with a rare multisystemic syndrome known as ataxia–telangiectasia (A–T)." (PMID 37296624, 2023). "The autosomal recessive disorder Ataxia-Telangiectasia is caused by a dysfunction of the stress response protein, ATM." (PMID 37830614, 2023). "Patients with ATM heterozygous mutations causing Ataxia-telangiectasia have genome instability and develop hematological malignancies such as leukemia and lymphoma, as well as immunodeficiency and neurodegeneration." (PMID 37989727, 2023). "The ataxia telangiectasia mutated (ATM) gene, identified on chromosome 11q22-23, can be altered and cause ataxia telangiectasia." (PMID 37205904, 2023). "In one female patient (#18) in this cohort, biallelic variants in the ATM gene were detected, proven to be pathogenic in a separate research project, leading to the diagnosis of variant ataxia-telangiectasia." (PMID 37131188, 2023). "ATM is considered as a tumour suppressor and patients with Ataxia telangiectasia (with homozygous ATM mutation) have extreme radiosensitivity, immunological deficiencies, neurodegeneration and cancer predisposition." (PMID 36606678, 2023). "Ataxia telangiectasia (AT) is an autosomal recessive disorder caused by the inactivation of the DNA damage sensor kinase ataxia telangiectasia mutated (ATM)." (PMID 37047099, 2023). "The autosomal‐recessive genome instability disorder, ataxia‐telangiectasia (A‐T) is caused by null alleles in the ATM gene, which encodes the ATM protein kinase." (PMID 37254625, 2023). "Friedreich ataxia, the most frequent recessive HCA, is caused by a biallelic intronic GAA expansion in the FXN gene, and ataxia–telangiectasia (the second most common recessive HCA in some series) arises from point mutations in the ATM gene." (PMID 37048110, 2023). "Biallelic pathogenic loss-of-function variants in ATM have long been associated with the genomic instability syndrome, ataxia-telangiectasia." (PMID 36865800, 2023).